SIRPD (signal regulatory protein delta)
Synonyms: PTPNS1L2; dJ576H24.4
Tractability: Antibody: UniProt places it where antibodies can reach, with high confidence; UniProt predicts a signal peptide or a membrane-spanning region; its Gene Ontology location is reachable by antibodies, with medium confidence.
Gene: Protein-coding gene on chromosome 20 (1,534,251 to 1,557,705, reverse strand). Ensembl gene ENSG00000125900.
Subcellular location: Secreted
Gene Ontology:
Cellular component: plasma membrane; extracellular region
Genetic constraint (gnomAD): Loss-of-function variants: 17 observed, 15.74 expected, observed/expected ratio (o/e) 1.08, 90% interval 0.74 to 1.61. The upper end of that interval is the gene's LOEUF score, 1.61, which puts it in group 6 of 6, group 1 being the genes least tolerant of losing a copy. Missense variants: 275 observed, 231.64 expected, observed/expected ratio (o/e) 1.19, 90% interval 1.08 to 1.31. Synonymous variants: 97 observed, 87.98 expected, observed/expected ratio (o/e) 1.1, 90% interval 0.93 to 1.3.
Homologues: Orthologues: chimpanzee SIRPD (95% identical). Paralogues in human: SIRPA (40% identical), SIRPG (40% identical), SIRPB1 (39% identical), SIRPB2 (27% identical).
Diseases named in the same sentence as SIRPD in open-access papers:
SIRPD is named in the same sentence as 4 diseases in open-access papers, as found by Europe PMC text mining. Sharing a sentence is not in itself a finding about the gene and the disease. The quoted sentences say what the papers report.
primary myelofibrosis (1 paper, 2022). Myelofibrosis with myeloid metaplasia is a myeloproliferative disease with annual incidence of approximately 1 case per 100,000 individuals and age at diagnosis around 60 (an increased prevalence is noted in Ashkenazi Jews). "While not much is known about SIRPD, the amplification of SIRPB1 has been associated with primary myelofibrosis, a disease of the bone marrow." (PMID 35887382, 2022).
SIRPD also shares sentences with these, for which no sentence is quoted: lung carcinoma (1 paper); meningioma (1); tumor (1).